RNU6-710P (RNA, U6 small nuclear 710, pseudogene)
Gene: Small nuclear RNA gene on chromosome 9 (111,996,635 to 111,996,739, reverse strand). Ensembl gene ENSG00000222356.
Homologues: Orthologues: chimpanzee U6 (98% identical), macaque U6 (91% identical), rat U6 (81% identical). Paralogues in human: RNU6-38P (87% identical), RNU6-1316P (86% identical), RNU6-393P (86% identical), RNU6-1145P (85% identical), RNU6-16P (85% identical), RNU6-20P (85% identical), RNU6-333P (85% identical), RNU6-35P (85% identical), RNU6-434P (85% identical), RNU6-46P (85% identical), RNU6-73P (85% identical), RNU6-1031P (84% identical), and 1284 more.